IL13 (interleukin 13)
Diseases named in the same sentence as IL13 in open-access papers (continued):
Sharing a sentence is not in itself a finding about the gene and the disease.
Obesity (continued). "Interleukin (IL)-1β and IL-13 were increased with obesity and age respectively." (PMID 29213245, 2017). "In future research, it might be promising to consider the role of anti-inflammatory cytokines such as IL-5, IL-10 and IL-13 in relation to physical activity in staying metabolically healthy despite the presence of obesity." (PMID 25781614, 2015). "Thus obesity-related differences in the ability of O3 to induce IL-13 expression appear to account for the ability of O3 to induce changes in baseline pulmonary mechanics in Cpefat but not WT mice." (PMID 23434795, 2013). "Importantly, obesity-related differences in IL-13 expression accounted for the ability of O3 to induce changes in the PV curve of lung and to increase baseline G and H in obese Cpefat but not lean WT mice." (PMID 23434795, 2013). "Notably, Il13 expression was reduced in the SVF (p=0.06), but highly increased in the adipocyte fraction of the Gipr-/- BM WAT, a phenomena associated with increased WAT inflammation during obesity." (PMID 33717200, 2021). "Likewise, a further study demonstrated that IL-13 gene transfer plays a protective role during experimental obesity by diminishing adipocyte hypertrophy, glucose intolerance, insulin resistance, and macrophage infiltration into adipose tissue of HFD-fed C57BL/6J mice." (PMID 29675435, 2018). "However, levels of IL-5, IL-6, and IL-13 went down in a dose-dependent manner and it could be interpreted that BoE supplementation could ameliorate the obesity related inflammatory features in the circulation system." (PMID 29292401, 2017). "Interestingly, adoptive transfer of CD4+ cells especially Th2 CD4+ T cells, which produce IL-4 and IL-13, rescues HFD-induced obesity and insulin resistance in Rag1 deficient mice suggesting that Th2 cytokines such as IL-4 and IL-13 suppress HFD-induced inflammation to improve insulin sensitivity." (PMID 23781214, 2013). "Consequently, to examine the hypothesis that IL-13 contributes to obesity-related differences in the response to O3, we measured IL-13 expression and examined the effects of anti–IL-13 antibodies in obese and lean mice." (PMID 23434795, 2013). "Regarding the correlation analyses of RAS components with hepatic cytokines in individuals with obesity and MASLD, a significant positive correlation was observed between ACE, and all analyzed cytokines (TNF-α, IL-6, IL-4, IL-13, IL-10)." (PMID 39337863, 2024). "Finally, we performed a gene correlation analysis of IL13 and IL4 expression with cytokine receptors, fibrosis markers, IL-13/IL-4 signaling components, and metabolic parameters in human WAT to address the clinical relevance of our data and potential association with parameters of obesity." (PMID 36982747, 2023). "The expression of IL-4, IL-13, and IL-5 decreased in HFD-fed mice and was restored by berberine, indicating that ILC2s inhibit obesity-related intestinal inflammation." (PMID 38283340, 2023). "For example, in 97 patients with obesity underwent either RYGB or biliopancreatic diversion with duodenal switch, decreased levels of IFN-γ, hs-CRP, TNF-α, IL-13, IL-6, IL-1ra, C3, and leptin were described compared with baseline levels at 1-year follow-up55." (PMID 34108550, 2021). "In similar studies, exposure to high fat diet during lactation (only) induced an early-onset obesity in offspring (C57BL/N mice) at 3 weeks of age, with increased expression of mRNAs of IL-5, IL-13, IL-17A and TNFα in the lung." (PMID 30700289, 2019). "Obesity also augments O3-induced increases in BAL CXCL1 and CXCL2, and BAL concentrations of the type 2 cytokines, IL-13 and IL-5." (PMID 27472835, 2017). "It is also noted that obesity in non-asthmatic adolescents is associated with increased sputum mRNA expression of IL6, IL8, IL13, IL17, IL23, and IFN-γ." (PMID 38629073, 2024).
Obesity (continued). "This review examines the major mechanisms between obesity and AD, which focus on the effect on skin and gut microbiota, immune responses mediated by the toll like receptor (TLR) signaling pathway, and changes in cytokine levels (TNF-a, IL-6, IL-4, and IL13)." (PMID 39564133, 2024). "Obesity had some influence on the cytokine/chemokine profile as shown by higher concentrations of IL-1ra and IL-13 in obese compared to non-obese OSA patients." (PMID 36769452, 2023). "Interestingly, obesity‐related leptin concentration significantly increased the ability of purified CD4+ T cells from lean AA patients to produce IL‐5, IL‐13, IL‐17 and IL‐6, but diminished IL‐10 release." (PMID 35734271, 2022). "Others have shown that serum and muscle IL-13 is reduced in non-obese patients with T2D, a common comorbidity of obesity." (PMID 32132925, 2020). "We found that plasma IL-8 and SPARC levels were reduced in the group of women with obesity, whereas plasma IL-13 concentrations were elevated in comparison to non-obese women both before and after the exercise bout." (PMID 32132925, 2020). "Unanswered questions include how the levels of type 2 inflammation, such as cytokines IL4, IL13, IL5, and adiponectin levels, both systemically but also locally in the airways, are affected in our model from the different stages of obesity and allergic inflammation." (PMID 33256137, 2020). "Levels of IL-12 were elevated in obesity, IFN-γ, IL-4, IL-5, IL-12 and IL-13 elevated in MetS." (PMID 25781614, 2015). "O3-induced increases in BAL LIX, a neutrophil chemotactic factor, were not affected by obesity, TNFR2 deficiency, or anti–IL-13 treatment indicating that this chemokine does not account for the observed effects on BAL neutrophils." (PMID 23434795, 2013). "To determine whether IL-13 contributed to obesity- and/or TNFR2-dependent changes in the response to O3, we treated mice with anti–IL-13 before O3 exposure." (PMID 23434795, 2013). "Because IL-13 has been shown to contribute to O3-induced AHR in lean BALB/c mice, we determined whether there were obesity- and/or TNFR2-dependent differences in IL-13 expression." (PMID 23434795, 2013). "Studies on mice have shown that overexpression of IL-13 prevents high-fat diet-induced weight gain without affecting food consumption, and administration of IL-4 increased brown fat mass and the thermogenic capacity to decrease established obesity." (PMID 32962676, 2020). "O3 also increased IL-13+ γδ T cells in mice with dietary obesity but not in lean controls." (PMID 27472835, 2017). "Apart from the crucial role of adipocyte- rather than macrophage-derived sPLA2-V in obesity, the Pla2g5 expression in macrophages is markedly induced by the M2-skewing Th2 cytokines IL-4 and IL-13 and the Pla2g5 ablation decreases the Th2-mediated immune responses." (PMID 29259680, 2016). "In summary, the results of our study indicate that subclinical inflammation, in terms of elevated IL-1β and IL-13, appears in PWS patients regardless of overweight or obesity." (PMID 32495042, 2021). "In order to investigate the role of a broad range of pro- and anti-inflammatory cytokines in obesity, serum levels of TNF-α, IFN-γ, IL-2, IL-4, IL-5, IL-10, IL-12, IL-13, and GM-CSF were compared between obese and non-obese participants." (PMID 25781614, 2015). "Most of the myokines measured were regulated by acute exercise (FGF21, IL-6, IL-8, IL-15, and IL-18), and some were released at different levels in plasma over the 24 h in the group of women with obesity in comparison to the non-obese group (SPARC, IL-8, and IL-13)." (PMID 32132925, 2020).
nasal polyps (78 papers, 2011 to 2026). "These environments are common during the formation of nasal polyps associated with aspirin intolerance, which is also marked by an increase in inflammatory mediators, especially IL-4, IL-5, and IL-13." (PMID 36721412, 2023). "We also observed that five days of treatment with a Th2 cytokine implicated in nasal polyp inflammation, IL-13, markedly down-regulated cilia-localized T2R4, 14, and 38 expression in well-differentiated (day 21) nasal ALIs." (PMID 35455449, 2022). "In our data, mast cells were distinguished by their expression of IL4 and IL13, which we also recently observed in a study of human nasal polyposis, a type 2 inflammatory disease associated with far-reaching epithelial remodeling." (PMID 35483355, 2022). "Molecularly genes related to the leukotriene pathway have been implicated and periostin, a biomarker of IL-13 activity, has been found in nasal polyps present in patients with AERD." (PMID 31294006, 2019). "Indeed, at the level of upper airways IL-4 and IL-13 play a key role in both inflammatory and structural changes (tissue remodelling) that underlie the formation of nasal polyps." (PMID 37063895, 2023). "In addition, the up-regulation of IL-13 expression in nasal polyp tissue is associated with the IL-13-induced increase in the number of M2 macrophages producing the coagulation factor XIIIA." (PMID 37240477, 2023). "IL-13 is a profibrotic cytokine, secreted from Th2 cells, associated to allergic inflammation and is involved in tissue remodeling, molecular mechanisms required for the transition to nasal polyp formation." (PMID 32961745, 2020). "Nasal polyps are benign lobular-shaped growths that project in the nasal cavities; they originate from inflammation in the paranasal mucous membrane and are associated with a high expression of interleukins (IL)-4, IL-5, IL-13, and IgE." (PMID 33287173, 2020). "ILC2s are enriched in nasal polyps from chronic rhinosinusitis patients and skin biopsies from atopic dermatitis patients and are among the main producers of IL-5 and IL-13 in the lungs of asthmatic patients." (PMID 39962262, 2025). "Dupilumab, targeting the IL-4 and IL-13 pathways, has demonstrated consistent benefits in reducing nasal polyp scores, improving olfaction, and delaying the need for revision surgery." (PMID 41011011, 2025). "OSM expression significantly increased in nasal polyp tissue from patients with chronic rhinosinusitis with nasal polyps and correlated with IL-13 expression in the sinus mucosa." (PMID 40677708, 2025). "The type 2 cytokines IL-4, IL-5, and IL-13, as well as IgE and eosinophils, play essential roles in sustaining inflammation and promoting the formation of nasal polyps." (PMID 39962262, 2025). "Through blocking IL-13 signaling, dupilumab disrupts this cycle of inflammation, reducing nasal polyps and improving mucosal function." (PMID 39768876, 2024). "By blocking the IL-13 pathways, dupilumab can reduce collagen deposition, fibrosis, and abnormal blood vessel formation within nasal polyps." (PMID 39063989, 2024). "Our study demonstrated that dupilumab, a monoclonal antibody targeting IL-4 and IL-13 signaling, was highly effective in improving the clinical outcomes of patients with chronic rhinosinusitis with nasal polyps (CRSwNP)." (PMID 39768876, 2024). "Staphylococcus aureus superantigens contribute to the polarization of type-2 immune response in nasal polyp tissue characterized by Th2 cytokines (IL-4, IL-5, IL-13) production and promote eosinophils infiltration." (PMID 37674852, 2023). "Nasal polyps with eosinophils infiltration are accompanied by type-2 inflammation expressing IL-4, IL-5, and IL-13 and high levels of circulatory but particularly local IgE." (PMID 37674852, 2023). "Airway remodeling elicited by IL-4 and IL-13 also occurs via their stimulatory action on M2-type macrophages, which promote fibrin deposition and nasal polyp formation by inhibiting fibrin degradation." (PMID 37240477, 2023).
nasal polyps (continued). "Nasal polyps show increased levels of mediators important for eosinophil accumulation and survival (e.g., IL-5 and IL-13) in comparison to healthy sinonasal tissue." (PMID 36986875, 2023). "A recent study found that Tnfsf11 was able to induce IL-5 and IL-13 in ILC2s via Tnfsf11a in chronic rhinosinusitis with nasal polyps." (PMID 37228603, 2023). "It has been demonstrated that Dupilumab (an anti IL-4/IL-13 biologic drug) is effective in reducing the size of nasal polyps and in improving patients’ symptoms and thus, quality of life." (PMID 37623491, 2023). "Within such an airway context, type 2 asthma and nasal polyposis develop as a consequence of the overexpression of IL-4, IL-13, and IL-5." (PMID 37240477, 2023). "Several works have reported that Dupilumab (an anti-IL-4/IL-13 biologic drug) effectively reduced the size of nasal polyps and improved the important parameters of disease burden in a number of patients." (PMID 37623491, 2023). "In an in vitro study using air liquid interface (ALI) cultures of primary bronchial epithelial cells treated with IL-5, IL-13, and IL-33, from patients with chronic rhinosinusitis with nasal polyps (CRSwNP), only IL-13 promoted RA generation." (PMID 36275689, 2022). "The α-toxin induces nasal polyp cells to produce large amounts of IL-5, IL-13, IFN-γ, IL-17A, and IL-10, which are involved in the inflammatory response." (PMID 35878202, 2022). "S. aureus binding to TLR 2 directly induces the release of epithelial cell-derived cytokines and promotes the expression of TSLP, IL-5, IL-13, and IL-33 in nasal polyp tissue." (PMID 35878202, 2022). "CRSwNP endotype markers with nasal polyposis indicate the desirability of using biological medicines targeting these receptors (IgE, IL-4, IL-5, and IL-13), especially in the treatment of CRS with nasal polyps and asthma (IL-5)." (PMID 35740420, 2022). "IL-4 along with IL-13 is one of the main cytokines driving type 2 inflammation in as much as 80% of patients with nasal polyps." (PMID 36285981, 2022). "IL-5 and IL-13 levels were significantly increased in the nasal polyps of patients with eCRSwNP (both P < 0.001) or noeCRSwNP (both P < 0.001), compared with control tissues." (PMID 35747690, 2022). "The treatment paradigm for nasal polyposis, previously managed with surgery and topical corticosteroids, has been revolutionized by inhibition of IL-4 and IL-13." (PMID 35608904, 2022). "Nasal polyp tissue (CRSwNP) displays robust levels of the cytokines IL-4, IL-5, and IL-13 compared to healthy controls, suggesting that they are key regulatory factors for eosinophil survival and activity." (PMID 32961745, 2020). "The target proteins, interleukin (IL)-4, IL-5, IL-13, and IgE were previously identified as key mediators in studies using nasal polyp tissues to measure and to interact in ex-vivo settings." (PMID 31452831, 2019). "Recently, it has been reported that there were significant increases in IL-13, IL-13Rα1, and IL-13Rα2 mRNA and protein concentrations in nasal polyp epithelium." (PMID 31866859, 2019). "Further work has shown that ILC2 from nasal polyps produce IL-13 in a GATA3-dependent manner after culture with IL-2, IL-33 and TSLP." (PMID 24876829, 2013). "The ERS/ATS group also noted that dupilumab may benefit patients with comorbid severe nasal polyposis, an IL-4/IL-13-driven condition." (PMID 40843371, 2025). "Furthermore, ILC2 derived from nasal polyp tissue also have the potential to produce more IL-5 and IL-13 compared to ILC2 from the nasal mucosa of healthy controls." (PMID 38540714, 2024). "Hence, IL-4 and IL-13 contribute remarkably to the massive eosinophil infiltration which often characterizes asthmatic bronchial walls, as well as the nasal polyps of patients with either CRSwNP or AERD." (PMID 37240477, 2023). "Pan-epithelial gene signatures in nasal polyps are imparted by IL-13 and prostaglandin E2." (PMID 35608904, 2022).
nasal polyps (continued). "Our results indicates that anti‐IL‐4/IL‐13 treatment might have utility for controlling the remodeling process within nasal polyps, which has been confirmed to effectively treat severe CRSwNPs." (PMID 34504680, 2021). "It has been reported that not only murine ILCs but also human blood and nasal polyp derived ILC2s could trans-differentiate by stimulation of a set of cytokines (IL-1β, IL-13, and TGF-β)." (PMID 32223753, 2020). "Approved biological therapies for nasal polyps include omalizumab, [a monoclonal antibody to immunoglobulin E (IgE)], mepolizumab [a monoclonal antibody to interleukin-5 (IL-5)], and dupilumab [a monoclonal antibody to the IL-4 receptor alpha subunit, blocking IL-4 and IL-13 activity]." (PMID 36970067, 2023). "We previously found that IL‐4 and IL‐13 could induce periostin expression in nasal polyps." (PMID 34504680, 2021). "Since the expression of eotaxin-3 in human nasal fibroblast is quite unknown, we established fibroblast lines from small pieces of human nasal polyps respectively, from 8 individuals and then examined eotaxin-3 protein secretion in fibroblasts stimulated by IL-13 for 48 h." (PMID 30778348, 2019). "Therefore, an anti-IL-13 strategy, such as tralokinumab, may be helpful in the management of patients with nasal polyps." (PMID 31866859, 2019). "Thus, our results suggest that IL13 is a candidate target for treatment of nasal polyposis." (PMID 21984922, 2011). "In our previous study, we found that SerpinB2 induced by IL-13 contributes to the expression of 15-lipoxygenase-1 (15LO1) and its downstream markers, such as CCL26 and iNOS in nasal polyp epithelial cells." (PMID 41142810, 2025). "Therefore, we hypothesize that IL-13 leads to the phosphorylation of related molecules of the mTOR/p70S6K1 pathway, promoting the proliferation and differentiation of the nasal epithelium, which leads to the generation of nasal polyps." (PMID 40438321, 2025). "This study assessed dupilumab, a monoclonal antibody targeting IL-4 and IL-13 signaling, to evaluate its efficacy in reducing the disease burden in patients with CRS with nasal polyps (CRSwNP)." (PMID 39768876, 2024). "Enriched blood and nasal polyp ILC2 cultured with TNF demonstrated a time- and dose-dependent production of IL-5 and IL-13, which was further enhanced in the presence of TSLP or IL-33 in vitro." (PMID 38540714, 2024). "This, in turn, results in the suppression of staphylococcal enterotoxin B-induced IL-5, IL-13, IFN-γ, and IL-17 production in nasal polyp cells." (PMID 36986875, 2023). "Th2 cytokines, such as IL-4 and IL-13, upregulate CCL17 expression in nasal polyp epithelium, whereas Th1 cytokines increase CCL17 levels in both normal and nasal polyp epithelium." (PMID 37762530, 2023). "The CRSwNP mainly showed Th2 cell inflammation, mainly involving the effects of IL-4, IL-5, and IL-13, accompanied by changes in IL-25, IL-33, TSLP and IgE levels, with eosinophil infiltration and nasal polyps phenomenon." (PMID 36506304, 2022). "In this study, we found that IL-5, IL-13, ECP, and eotaxin levels were significantly increased in the nasal polyps of patients with eCRSwNP or noeCRSwNP, whereas IL-4 levels were only increased in patients with eCRSwNP." (PMID 35747690, 2022). "Type 2 inflammatory cytokines such as IL-4, IL-13, IL-8, and IL-33 in CRSwNP patients enhanced expression of MUC5AC in nasal polyp-derived epithelial cells." (PMID 36506304, 2022). "Levels of IL-4, IL-5, IL-13, and ECP and the eotaxins CCL11, CCL24, and CCL26 were elevated in the nasal polyps of patients with eCRSwNP or noeCRSwNP." (PMID 35747690, 2022). "In an experimental study using organ culture of nasal polyps, S. aureus infection promoted the release of MMP-2, MMP-9, TIMP-1, and Th2 cytokines, including IL-5, IL-13, and eotaxin." (PMID 33477617, 2021).